TFF3 (trefoil factor 3)
Diseases named in the same sentence as TFF3 in open-access papers (continued):
Sharing a sentence is not in itself a finding about the gene and the disease.
glioma (1 paper, 2017). A benign or malignant brain and spinal cord tumor that arises from glial cells (astrocytes, oligodendrocytes, ependymal cells). "To explore the mechanism whereby TFF3 regulates glioma cell motility, we measured expression of the invasion- associated molecules MMP-2, finding that their protein levels significantly decreased after TFF3 knockdown in U87 and U251 cells." (PMID 29100347, 2017). "Putting all data together, we conclude that Akt/Caspase signaling pathway involves in TFF3 protection against apoptosis in glioma." (PMID 29100347, 2017). "Here, we report that expression level of TFF3 significantly elevated in glioma and correlated with the prognosis of glioma patients." (PMID 29100347, 2017). "The results showed that TFF3 was also higher in glioma than in normal brain tissues and was higher in high-grade (WHO grades III and IV) than low-grade (WHO grades I and II) glioma samples." (PMID 29100347, 2017). "The aim of this study was to identify the role of which TFF3 plays as a potential oncoprotein that influences various aspects of glioma cell maneuver via regulating HIF-1α." (PMID 29100347, 2017). "In conclusion, TFF3 drives aberrant glioma cells proliferation and invasion in vivo and in vitro through a hypoxia-independent HIF-1α induction." (PMID 29100347, 2017). "Then we found TFF3 promotes proliferation, invasion, and migration and inhibits apoptosis of glioma cells in vitro, and delayed tumor progression in subcutaneous xenograft nude mice, and prolonged the median survival time in orthotopic xenograft mice." (PMID 29100347, 2017). "Expression level of TFF3 was investigated in 92 glioma specimens and five normal brain tissue specimens by using immunohistochemistry." (PMID 29100347, 2017). "Here, we show a hypoxia-independent mechanism of HIF-1α induction in glioma, in which TFF3 cooperates with HIF-1α by upregulating its expression and transcriptional activity." (PMID 29100347, 2017). "In this study, we focused on the role of TFF3 in glioma development and identified TFF3 as an oncoprotein in glioma." (PMID 29100347, 2017). "In order to identify the function of TFF3 and HIF-1α playing in glioma, we constructed U87 and U251 TFF3-knockdown/ HIF-1α-knockdown stable cell lines." (PMID 29100347, 2017). "Stable knockdown of TFF3 significantly reduced glioma cells proliferation and invasion in vitro and suppressed the tumor volumes in vivo." (PMID 29100347, 2017). "TFF3 mRNA expression also increased in glioma cell lines (P=0.003)." (PMID 29100347, 2017). "The levels of TFF3 mRNA were significantly augmented in high-grade than low-grade gliomas (P<0.01)." (PMID 29100347, 2017). "Likewise, TFF3 expression correlates with the WHO grade of glioma, regulating the expression and transcriptional activity of HIF-1α under normoxic conditions." (PMID 29100347, 2017). "Parallel with HIF-1α, the expression of TFF3 was correlated with the WHO grade of gliomas." (PMID 29100347, 2017). "Here, we find that TFF3 is overexpressed in glioma cell line and in glioma tissues." (PMID 29100347, 2017). "Importantly, patients with glioma expressing low levels of TFF3 have significantly prolonged survival time compared to those expressing high levels of this gene." (PMID 29100347, 2017). "Since TFF3 was cooperated with HIF-1α to promote the tumorigenesis of glioma, we tried to investigate whether TFF3 regulates the expression of HIF-1α, Western blotting analysis was performed." (PMID 29100347, 2017). "Thus, inhibition of TFF3 may offer a selective therapeutic strategy for targeting expression of HIF-1α in gliomas." (PMID 29100347, 2017). "We tested the hypothesis that TFF3 regulating glioma cell proliferation, migration and invasion." (PMID 29100347, 2017). "The result suggested that TFF3 could bind to HIF-1α in glioma cell lines." (PMID 29100347, 2017).
glioma (continued). "We also found that TFF3 promotes cell proliferation, cell metastasis and inhibits cell apoptosis by regulating Hypoxia-Inducible Factor -1α (HIF-1α) under normoxic conditions in glioma cell in vitro." (PMID 29100347, 2017). "Therefore, we presume that TFF3 regulates the transcriptional activity of HIF-1α and thus promotes glioma cells proliferation, migration and invasion." (PMID 29100347, 2017). "In this assay, knockdown of TFF3 upregulated cleaved Caspase3/9 expression and suppressed p-AKT expression and thus promoted tumor cells apoptosis, which suggested that TFF3 blocked apoptosis in glioma cell lines." (PMID 29100347, 2017). "As a corollary, although the mechanism of TFF3-HIF-1α interaction needs further investigation, inhibition of TFF3 might offer a novel strategy to target HIF-1α and retard glioma progression." (PMID 29100347, 2017). "Similar to the results of TFF3 expression in different grade glioma samples, higher HIF-1α expression was found in high-grade (WHO grades III and IV) than low-grade (WHO grades I and II) glioma tissues, showing a statistically significant difference between these groups (P<0.001)." (PMID 29100347, 2017). "However, the regulation between TFF3 and HIF-1α has not yet been elucidated in glioma." (PMID 29100347, 2017).
Glucose intolerance (1 paper, 2013). Glucose intolerance (GI) can be defined as dysglycemia that comprises both prediabetes and diabetes. "To eliminate concerns related to potential impact of leptin signaling deficiency in db/db or ob/ob mice, we examined the effects of Tff3 activation on glucose intolerance and insulin resistance in diet-induced obese (DIO) mice." (PMID 24086476, 2013). "GTT experiments showed that blood glucose level at each time point tested in Ad-Tff3-infected mice were lower than that in Ad-GFP-infected control mice, suggesting that Tff3 activation improved glucose intolerance in db/db mice." (PMID 24086476, 2013). "Based on the facts that adenovirus can also effectively infect immune cells, including macrophage, we cannot rule out the possibility that injected adenovirus expressing Tff3 infected immune cells and decreased cytokine secretions, thereby improving glucose intolerance in diabetic mice." (PMID 24086476, 2013). "GTT experiments indicated that overexpression of Tff3 improved glucose intolerance, while ITT and PTT experiments suggested that Tff3 activation modestly enhanced insulin sensitivity and decreased glucose production in vivo in ob/ob mice, respectively." (PMID 24086476, 2013).
gynecological cancers (1 paper, 2022). "TFF3 alterations have been demonstrated also in gynecological cancers, such as endometrial and ovarian tumors." (PMID 35461390, 2022).
Hearing impairment (1 paper, 2022). A decreased magnitude of the sensory perception of sound. "In summary, phenotypic changes caused by TFF3 deficiency include intestinal epithelial and corneal regeneration defects, accelerated presbyopia and hearing impairment, weight loss, abnormal lipid metabolism, and impaired vascular function." (PMID 35039476, 2022).
Helicobacter infection (1 paper, 2017). "Taken together, these data suggest that TFF1 is induced upon Helicobacter infection in both cellular systems, while TFF2 and TFF3 responses change depending on the host system." (PMID 29085807, 2017).
herpetic keratitis (1 paper, 2021). "TFF3 also found to be upregulated in our sample has already been related to corneal inflammation in dry eye disease herpetic keratitis." (PMID 34615949, 2021).
hookworm infection (1 paper, 2021). "Overall, TFF2 elevation is specifically associated with Hookworm infection, especially in females, while TFF3 elevation is associated with Schistosoma infection and females have higher levels in general in a mostly adult population." (PMID 34662329, 2021). "We have previously shown critical roles for TFF2, TFF3 and the alarmin cytokine IL-33 in protective immune responses in a murine model of hookworm infection, which needs to be confirmed in human infection." (PMID 34662329, 2021). "In contrast to hookworm infection, S. hematobium infection in children was associated with a decrease in both TFF2 and TFF3 in the serum, but not the urine." (PMID 34662329, 2021). "This response was significantly repressed by co-treatment with rh-TFF2, but not rh-TFF3, indicating that elevated TFF2 could contribute to suppressed inflammatory responses in the context of hookworm infection." (PMID 34662329, 2021).
Hyperglycemia (1 paper, 2013). An increased concentration of glucose in the blood. "Tff3 alleviates hyperglycemia in diabetic mice by suppressing hepatic gluconeogenesis." (PMID 24086476, 2013).
Hypoglycemia (1 paper, 2022). A decreased concentration of glucose in the blood. "Similar to TFF3, I-FABP was elevated in children with AKI and acidosis as well as children with hypoglycemia and hypoxemia on admission." (PMID 36069443, 2022).
immune complex disease (1 paper, 2023). "As FIP is an immune complex disease, one can speculate that suppressing the expression of proteins such as IAP and TFF‐3 and stimulating the expression of proteins such as I‐FABP may affect disease progression." (PMID 37872840, 2023).
Insulin resistance (1 paper, 2013). Increased resistance towards insulin, that is, diminished effectiveness of insulin in reducing blood glucose levels. "In this study, we found that the expression levels of Tff3, a secretory protein which is the most widely expressed peptide in the TFF family in multiple tissues, were reduced in liver of mice with insulin resistance." (PMID 24086476, 2013).
invasive breast carcinoma (1 paper, 2019). A carcinoma that infiltrates the breast parenchyma. "Variable expression of TFF3 has been detected in invasive breast carcinoma; some have shown diminished expression while others have demonstrated increased expression." (PMID 30744593, 2019). "There was a variable expression of TFF3 by invasive breast carcinomas." (PMID 30744593, 2019). "It is noteworthy to mention here that many of the residual clusters of invasive breast carcinoma that show high expression of TFF3 have no apoptotic cells." (PMID 30744593, 2019).
invasive carcinoma (1 paper, 2019). A carcinoma that is not confined to the epithelium, and has spread to the surrounding stroma. "This is compatible with our finding of co-localization of TFF3 and BCl2 in residual invasive carcinoma in incomplete pathological response group." (PMID 30744593, 2019). "There was increased expression of TFF3 in residual invasive carcinoma cells." (PMID 30744593, 2019).
ischemic stroke (1 paper, 2022). A stroke disorder caused by obstruction of blood flow to the brain, due to thrombotic (local blood clot formation) or embolic (due to a blood clot or other material traveling from another site) event. "TFF3 is a protective marker of underlying myocyte damage/ischemia and is moderately correlated with ischemic stroke in patients with AF." (PMID 36704472, 2022).
kidney injury (1 paper, 2020). Trauma to the kidney. "TFF3 has been suggested to be a highly sensitive and specific urinary biomarker to monitor drug-induced kidney injury in clinical trials." (PMID 33134397, 2020).
liver disease (1 paper, 2019). "The novel congenic mouse strain Tff3−/−/C57BL6NCrl is a valuable model for assessing the role of Tff3 deficiency on liver disease relevant pathways." (PMID 31500117, 2019).
lung disease (1 paper, 2022). "Trefoil factor 3 was neither detectable in the lungs of wild-type mice nor in those of the CF-like lung disease." (PMID 35249163, 2022).
malignant glioma (1 paper, 2017). A grade III or grade IV glioma arising from the central nervous system. "Then, we measured the TFF3 mRNA expression in five malignant glioma cell lines (U87, U373, U251 T98G and LN229) and five normal brains as control." (PMID 29100347, 2017). "However, the expression and biological function of TFF3 in malignant gliomas is not clear." (PMID 29100347, 2017).
medullary carcinomas (1 paper, 2004). "Normal thyroids, adenomatous goitres and medullary carcinomas overexpress TFF3 mRNA." (PMID 15083192, 2004).
metabolic syndrome (1 paper, 2022). A cluster of metabolic risk factors for CARDIOVASCULAR DISEASES and TYPE 2 DIABETES MELLITUS. "Overall, the involvement of Tff3 in regulation of lipid metabolism identified it as a possible candidate for treatment of hepatic manifestations of metabolic syndrome." (PMID 36013467, 2022). "Therefore, 8 months (35 weeks) of HFD treatment was used to induce the metabolic syndrome in male and female congenic Tff3-/- mice and corresponding WT controls (C57Bl6N)." (PMID 36013467, 2022). "Newly generated Tff3-/- mice and appropriate WT controls of both sexes were fed a high-fat diet (HFD) for 8 months to induce metabolic syndrome conditions, including fatty liver phenotype." (PMID 36013467, 2022).
myocardial ischemia (1 paper, 2013). A disorder of cardiac function caused by insufficient blood flow to the muscle tissue of the heart. "We have recently demonstrated that experimental myocardial ischemia in the mouse causes upregulation and release of secretory proteins, including TFF3." (PMID 24204940, 2013). "We have recently demonstrated an endocrine cardioprotective mechanism in experimental myocardial ischemia involving upregulation of secretory proteins, including TFF3, in the liver." (PMID 24204940, 2013).
nasal polyps (1 paper, 2019). "In our study, we were able to detect mRNA levels of TFF1 and TFF3 genes and proteins in all samples from both CRSwNP (nasal polyps, bulla ethmoidalis, and middle nasal turbinate) and control patients (inferior nasal turbinate)." (PMID 31683988, 2019). "TFF1 and TFF3 expression levels in sinonasal mucosa and nasal polyps were compared between the patients with positive sinus swabs and the group of patients whose swabs were sterile." (PMID 31683988, 2019). "We would like to emphasize that our study is the first to assess and analyze the expression pattern of TFF1 and TFF3 genes and peptides in a representative number of nasal polyp tissues collected from CRSwNP patients." (PMID 31683988, 2019). "Data on TFF expression in sinonasal mucosa and nasal polyp tissue from CRSwNP are scarce, thus, the aim of this study was to assess expression levels of TFF1 and TFF3 genes in patients with CRSwNP and a control group of patients undergoing septoplasty." (PMID 31683988, 2019). "Expressions of TFF1 and TFF3 were determined in specimens of middle nasal turbinate (MNT-0), bulla ethmoidalis (BE), and nasal polyps (NP) from CRSwNP patients (n = 29) and inferior nasal turbinate from a group of control patients (underwent nasal septoplasty, n = 25)." (PMID 31683988, 2019).
oesophagitis (1 paper, 2025).
oral cancer (1 paper, 2021). "Thus, the application particularly of homodimeric TFF3 in oral cancer patients during chemotherapy needs caution and should be investigated in detail as it has the potential to act as a double-edged sword." (PMID 34830103, 2021).
osteoarthritis (1 paper, 2019). A noninflammatory degenerative joint disease occurring chiefly in older persons, characterized by degeneration of the articular cartilage, hypertrophy of bone at the margins and changes in the synovial membrane. "Gene expression of TFF1, TFF2, and TFF3 of healthy, osteoarthritis (OA), and rheumatoid arthritis (RA) affected SM was analyzed by semi-quantitative PCR." (PMID 31817054, 2019). "In the past, we described TFF3 production by human articular chondrocytes if the cartilage was affected by osteoarthritis (OA) with chondrocytes of healthy articular cartilage having been TFF3-negative." (PMID 31817054, 2019).
periodontal disease (1 paper, 2024). "In conclusion clinical andbiochemical analysis of serum TFF3 revealed its influence on periodontal disease activity." (PMID 39917209, 2024).
pituitary adenoma (1 paper, 2019). "It clearly demonstrated that TFF3 protein knockout can accelerate the apoptosis in human pituitary adenoma cells via mitochondrial apoptosis pathway." (PMID 31649621, 2019). "For example, trefoil factor 3 (TFF3) is an apoptosis-related protein, and its knockout in human pituitary adenoma cell line decreased the levels of apoptosis-related proteins Bcl-2 and caspase-3, and increased the levels of Bax and cleaved caspase-3." (PMID 31649621, 2019).
Pleural effusion (1 paper, 2025). The presence of an excessive amount of fluid in the pleural cavity. "In liver metastasis BL T cells, granzyme family genes (GZMA, GZMH, and GNLY) were enriched, while pleural effusion BL T cells showed increased TFF3, AGR2, MGP, and MIF expression." (PMID 39955556, 2025).
prostate adenocarcinoma (1 paper, 2023). "This study aimed to investigate the relationship between renal function parameters and distinctive molecular subtypes of prostate adenocarcinomas, defined by the immunoexpression of the SPINK1, ERG, HOXB13, and TFF3 markers." (PMID 37894380, 2023).
prostate intraepithelial neoplasia (1 paper, 2017). A neoplastic proliferation of the epithelial cells that line the acini and the ducts of the prostate gland. "To investigate the diagnostic potential of TFF3 promoter hypomethylation, we used qMSP to analyze TFF3 promoter methylation levels in 15 BPH, 18 adjacent normal (AN), 11 prostate intraepithelial neoplasia (PIN), and 292 PC tissue samples from a large RP cohort with long clinical follow-up." (PMID 28930171, 2017).
prostate tumor (1 paper, 2023). "On the other hand, the possible mechanism by which TFF3 promotes prostate tumor progression is not fully understood." (PMID 37894380, 2023).
psoriasis (1 paper, 2017). An autoimmune condition characterized by red, well-delineated plaques with silvery scales that are usually on the extensor surfaces and scalp. "In silico-based expression analysis revealed TFF3-mediated regulation of selected microRNAs as well as long non-coding RNAs (lncRNAs), whereas miR-491-5p was identified to target the lncRNA ‘psoriasis susceptibility-related RNA gene induced by stress’ (PRINS)." (PMID 28149533, 2017).
renal cell carcinoma (1 paper, 2017). "In patients with renal cell carcinoma expression of TFF peptides are highly upregulated along the urinary tract with TFF3 being the most prominent one." (PMID 28355260, 2017).
secondary carcinoma (1 paper, 2013). A carcinoma that arises from a pre-existing lower grade epithelial lesion, or as a result of a primary carcinoma that has spread to secondary sites, or due to a complication of a cancer treatment. "The mean serum concentrations of TFF3 in patients with CKD, metastatic and secondary carcinoma (MC) and acute gastroenteritis (AG) (200.9 ng/ml, 95.7 ng/ml and 71.7 ng/ml, respectively) were significantly higher than those in patients with other common clinical diseases." (PMID 24282531, 2013).
Sjögren’s syndrome (1 paper, 2023). "In addition, circulating levels of TFF3 were significantly increased in patients with Sjögren’s syndrome secondary to RA compared with healthy controls." (PMID 36973646, 2023).
Splenomegaly (1 paper, 2024). Abnormal increased size of the spleen. "The T2DM modeling led to splenomegaly in mice, and increased expression of TFF3 in their spleens." (PMID 38710764, 2024).
thyroid follicular carcinomas (1 paper, 2004). "On the other hand, three of the four follicular carcinomas with high expression levels of TFF3 were pathologically questionable." (PMID 15083192, 2004).
vaginal infection (1 paper, 2024). "Thus, it would be interesting to test whether Tff3-deficient mice show pre-term birth after vaginal infection as reported for Muc5b-deficient mice due to a porous cervical mucus plug." (PMID 38396964, 2024).